BLM (BLM RecQ like helicase)
Diseases named in the same sentence as BLM in open-access papers (continued):
Sharing a sentence is not in itself a finding about the gene and the disease.
tumor (continued). "Under suboptimal cultivation conditions (no filter support or low oxygen with filter support), the down-regulation of BRCA1 and BLM (DDR) and up-regulation of HERPUD1 was common to slices from all three tumour xenograft models." (PMID 26647838, 2015). "We analyzed the ROC curves for all previously known potential factors, including age, tumor size, hemoglobin, along with our potential markers: BRCA1, BRCA2, RAD51, FANCD2, BLM and BRIP1." (PMID 24708616, 2014). "We found that EPI inhibited tumor growth in the CDXE-resistant BKO model and that overexpression of BLM-WT but not the K24R mutant rescued tumor growth in vivo." (PMID 40634292, 2025). "A few of the major tumor suppressors like BRCA1 and RB may impact or regulate BLM or could be a common target of tumor suppressors." (PMID 33777104, 2021). "Our current research has revealed that BLM expression is increased in CCA tissues compared with paracancerous samples, which has been further verified in assays in vitro, and high BLM expression is correlated with the tumor progression and adverse prognosis." (PMID 33828983, 2021). "It has been reported that tumors in BLM mutation carriers do not demonstrate LOH, and normal BLM protein is expressed in tumor cells." (PMID 31614901, 2019). "Selected CRC target genes involved in apoptosis (BAX), tumor growth (TGFβRII), WNT pathway (AXIN2, TCF4, WISP3), DNA repair (ATM, ATR, BLM, BRCA1, BRCA2, DNAPKcs, MBD4, MRE11, MSH3, MSH6, RAD50, XRCC2) and PI3-kinase signaling (PTEN) were analyzed for mutations in MSI-positive HGG samples." (PMID 21637783, 2011). "Currently, no separation-of-function mutations have been identified that could distinguish the roles of BLM in double Holliday junction (dHJ) dissolution, DNA-end resection, UFB processing, and stalled fork restart, to prove which contribute to tumor suppression in a suitable animal model." (PMID 33500419, 2021). "Furthermore, we detected the BLM expression in vitro, and the results demonstrated that the expression level of BLM was much higher in the CCA tissues and cells relative to adjacent non-tumor samples and normal bile duct epithelial cells." (PMID 33828983, 2021). "Phosphorylated BLM may then bind to Polo-like kinase 1 (PLK1) via its polo-box domain (PBD), further contributing to the maintenance of genomic stability in both healthy and tumor tissues." (PMID 31210839, 2019).
genetic disorders (15 papers, 2011 to 2025). "Mutations in WRN and BLM are associated with the rare genetic diseases Werner and Bloom syndromes, respectively." (PMID 25400656, 2014). "Mutations in WRN, BLM, or RECQL4 cause different genetic disorders, all associated with accelerated aging, genomic instability and tumorigenesis." (PMID 32820027, 2020). "WRN, BLM, and RTS are involved in genetic disorders associated with genomic instability and a high incidence of cancer." (PMID 25424877, 2014).
infection (7 papers, 2015 to 2025). The state of being infected such as from the introduction of a foreign agent such as serum, vaccine, antigenic substance or organism. "At 16 h after infection, compared to the mutants, levels of BLM mRNA were highest in cells infected with dl309, expressing wt E1A." (PMID 29257057, 2017). "dl1133 had the second highest BLM mRNA levels, while dl311, dl1135 and dl1136 had the lowest levels at 16 h after infection." (PMID 29257057, 2017). "Overall, infection with dl309 induced expression of BLM, MCM4, and PCNA to levels higher than dl520 infection, and with the exception of PCNA to levels similar to those observed in pm975-infected cells." (PMID 26448631, 2015). "Interestingly, dl1135, which had very low levels of induction of BLM at 16 h, was able to recover later, particularly at 48 and 72 h after infection." (PMID 29257057, 2017). "We therefore used one such virus, hr703, to examine BLM levels during infection." (PMID 25794620, 2015). "Although BLM has previously been implicated in double-strand DNA break repair, its mRNA levels did not decrease nor were they elevated early in infection." (PMID 26448631, 2015). "Other DDR proteins degraded during Ad5 and Ad12 infection include MRE11, DNA ligase IV, and Bloom syndrome RecQ-like helicase (BLM)." (PMID 29593045, 2018). "Lastly, induction of MCM4 lagged behind that of BLM and PCNA and correlated closely with initiation of viral DNA replication, with levels of MCM4 mRNA increasing at 48 h after infection in these cells." (PMID 29257057, 2017). "We looked at expression of Bloom (BLM), Proliferating Cell Nuclear Antigen (PCNA) and Mini-Chromosome Maintenance 4 (MCM4) at 16, 24, 48 and 72 h after infection as compared to mock infected cells." (PMID 29257057, 2017). "Expression of BLM, MCM4, and PCNA was unaltered at 8 hours after infection as compared to mock-infected cells." (PMID 26448631, 2015). "This trend continued later into the infection particularly with dl311 and dl1136, which never induced BLM expression beyond 2-fold over mock infected cells." (PMID 29257057, 2017). "At 16 hours after infection, BLM transcript levels increased slightly in pm975-infected cells, but not others, whereas PCNA mRNA was elevated for all infections." (PMID 26448631, 2015).
adenocarcinoma (1 paper, 2018). A common cancer characterized by the presence of malignant glandular cells.
BLM also shares sentences with these, for which no sentence is quoted: hematologic malignancies (4 papers); sarcoma (4); ataxia telangiectasia (3); Li-Fraumeni syndrome (3); progeria (3); xeroderma pigmentosum (3); autosomal recessive disease (2); chordoma (2); congenital ichthyosis (2); Insulin resistance (2); Lung squamous cell carcinoma (2); myelodysplastic syndrome (2); T cell lymphoma (2); Wilms tumor (2); adenovirus infection (1); Alzheimer disease (1); Baller-Gerold syndrome (1); bone tumors (1); B‐cell lymphomas (1); cervical squamous cell carcinoma (1); childhood cancer (1); chromosomal instability syndrome (1); colorectal polyps (1); Cowden syndrome (1); deafness (1); diabetes mellitus (1); Diamond-Blackfan anemia (1); Duchenne muscular dystrophy (1); endocervical adenocarcinoma (1); epidermolysis bullosa simplex (1).
A further 42 diseases each share a sentence with BLM in 1 paper.